IL6 (interleukin 6)
Diseases named in the same sentence as IL6 in open-access papers (continued):
Sharing a sentence is not in itself a finding about the gene and the disease.
lung carcinoma (continued). "In addition, within lung cancer cells, IL-6 secreted by TAMs activates the cyclooxygenase 2 (COX2), prostaglandin E2 (PGE2), and β-catenin signaling pathways, which activate EMT and cell invasion." (PMID 37050907, 2023). "We also found that EGFR TKIs enhanced IL6 mRNA expression in CDCP1 knockdown lung cancer cells." (PMID 37013960, 2023). "inhibits lung cancer cells by regulating the IL-6-induced JAK2/STAT3 pathway." (PMID 37291549, 2023). "In this study, serum levels of IL-6, IL-1β, and IFN-γ were associated with lung cancer risk." (PMID 38067398, 2023). "IL-6 from CD10+ GPR77+ CAFs promoted tumor formation in lung cancer." (PMID 37480115, 2023). "A potent cytokine, IL-6, plays an important role in lung cancer development." (PMID 37192201, 2023). "Similar to IL-1β, high levels of IL-6 may contribute to the growth, metastasis, and immune escape of lung cancer cells." (PMID 37033918, 2023). "Some cytokines, like IL-6, could be remarkably elevated in lung cancer patients in particular for those who underwent surgery." (PMID 37986068, 2023). "Interestingly, it was demonstrated that IL-6 blockade significantly inhibited lung cancer promotion, tumour cell-intrinsic STAT3 activation, tumour cell proliferation, and angiogenesis markers." (PMID 37569672, 2023). "Many studies have indicated that abnormally elevated IL-6 predicts poor survival in lung cancer." (PMID 36814297, 2023). "Notably, several of the proteins most strongly associated with lung cancer, including CEACAM5, IL6, and SCF, were weakly correlated with other markers and did not have any stable connections with other identified risk markers." (PMID 37264016, 2023). "CAFs are known to enhance the metastatic ability of lung cancer cells via IL-6/STAT3 signaling." (PMID 36831295, 2023). "Moreover, the ROC plot analysis revealed that several inflammatory markers, including IL-1b, IL-2, IL-6, IL-10, IL-12p70, and TNF-alpha, are significantly associated with the risk of lung cancer." (PMID 37373957, 2023). "This pathway can drive the secretion of IL6 in KRAS-mutant lung cancer." (PMID 37581538, 2023). "Lack of SIRPα suppressed lung cancer cell growth in mice, dependent on circulating macrophages and neutrophils, in association with improved phagocytosis and reduced IL‐6 expression." (PMID 36419386, 2023). "Furthermore, the regression analysis demonstrated that patients with lung cancer had significantly higher odds for increased levels of IL-1b, IL-2, IL-6, and IL-12p70 above the calculated cut-off values." (PMID 37373957, 2023). "Indeed, pharmacologic blockade of IL6 in a mouse model of KRAS-mutant lung cancer results in a reduction in protumorigenic macrophages and Tregs with concomitant activation of CD8+ T cells." (PMID 37581538, 2023). "It is noteworthy that IL-6 could not only promote the cell proliferation, induce treatment resistance, and promote metastasis in lung cancer but also promote the expansion of the CSCs." (PMID 37986068, 2023). "Additionally, endurance exercise downregulates TNF-α and iNOS expression in lung cancer tissue but upregulates IL-6 and IL-10 expression." (PMID 37691942, 2023). "CD10+/GPR77+ CAFs could promote drug resistance in patients with lung cancer by secreting IL-6 and IL-8 to maintain the stemness of cancer stem cells." (PMID 37144123, 2023). "Ten blood cytokine levels, including; granulocyte-macrophage colony-stimulating factor, TNF (alpha), and IFN (gamma), IL1, IL6, IL12, IL4, IL8, IL10, IL5, were compared between 296 European-Americans and 170 African-Americans to determine their associations with lung cancer." (PMID 36874133, 2023). "Additionally, incubating lung cancer cells with macrophages boosted the production of IL-1b and IL-6, which further encouraged the lung cancer cells to produce SAA1/2." (PMID 37444523, 2023).
lung carcinoma (continued). "In conclusion, high IL‐6 content in peripheral blood in patients with advanced non‐small cell lung cancer may contribute to poor anti‐PD‐1 efficacy and short duration of PFS through inducing alterations in the tumor microenvironment." (PMID 37326149, 2023). "High IL‐6 content in peripheral blood in patients with advanced non‐small cell lung cancer may contribute to poor anti‐PD‐1 efficacy and short duration of PFS through inducing alterations in the tumor microenvironment." (PMID 37326149, 2023). "Furthermore, the restoration of IL-6 expression in M2 macrophages enhances migration, chemotaxis, and angiogenesis in lung cancer cells." (PMID 35036439, 2022). "According to the findings of this study, ERβ/IL6 may represent prospective therapeutic targets for prognosis and interventions in lung cancer." (PMID 35631448, 2022). "While hepcidin and CRP examination may point to the pathogenesis of anaemia, we discovered that hepcidin and IL-6 examination may predict the development of anaemia during hospitalization in female lung cancer patients." (PMID 36612220, 2022). "Indeed, we found that expression of IL-1β, IL-6 and TNFα was dramatically reduced in lung cancer cells in response to BAY11-7082 treatment." (PMID 36457047, 2022). "In summary, our study suggests that serum IL-1β, IL-6, and IL-8 might serve as potential markers for the diagnosis of lung cancer." (PMID 35928100, 2022). "The results suggest that serum IL-1β, IL-6, and IL-8 are highly expressed in lung cancer, which might be considered potential biomarkers for lung cancer." (PMID 35928100, 2022). "The expression level of GPX8 was positively correlated with CCL2 and IL6 in lung cancer." (PMID 35978854, 2022). "AKIRIN2 is necessary for the growth and metastasis of lung cancer and liver cancer and promotes the angiogenesis of gallbladder cancer through interleukin-6 (IL-6)/signal transducer and activator of transcription 3 (STAT3)/vascular endothelial growth factor A (VEGFA)." (PMID 36059811, 2022). "Elevated serum IL-6 levels in patients with lung cancer predict adverse clinical outcomes." (PMID 36591515, 2022). "Using the CRISPR-ELISA assay to profile plasma cytokines in 127 lung cancer patients and 125 cancer-free smokers, we develop a panel of plasma cytokine biomarkers (IL-6, IL-8, and IL-10) for early detection of the disease, with 80.6% sensitivity and 82.0% specificity." (PMID 36498497, 2022). "Interestingly, activation of NF-κB has been reported to actively shape tumor microenvironment of lung cancer through upregulating the expression of inflammatory cytokines like IL-6 and activation of STAT3 signaling." (PMID 36457047, 2022). "The relatively high levels of inflammatory cytokines, such as IL-6, in patients undergoing hemodialysis (median, 7.1 pg/mL; range, 2.2–163.5 pg/mL), those with lung cancer (mean, 30.3 ± 40.2 pg/mL), and those with Crohn disease (mean, 13.8 ± 13.4 pg/mL), show a positive correlation with REE." (PMID 35369060, 2022). "We were only able to detect TNF-α and IL-6, implying that these two cytokines could be mainly involved in S1P-mediated inflammatory signaling in lung cancer-derived PBMCs." (PMID 36010601, 2022). "have indicated that the up‐regulation of IL‐6/STAT signal transduction may be a contributor to EGFR‐TKIs resistance in lung cancer." (PMID 35605028, 2022). "Indeed, many studies correlate high levels of IL-6 in the blood of lung cancer patients with poor prognosis and drug resistance, although the mechanism is still unclear." (PMID 36010601, 2022). "In addition to reduced CRP and IL-6 levels, cardiovascular events and death, canakinumab treatment lowered lung cancer incidence and mortality as well as total cancer mortality vs. placebo." (PMID 35406394, 2022).
lung carcinoma (continued). "In addition, blocking PI3K/AKT, as the downstream pathway activated by IL6, can inhibit the differentiation of osteoclasts induced by lung cancer cells or interleukins, which highlights the important role of IL6 in bone homeostasis." (PMID 35872837, 2022). "Attempts to use an IL-6-blocking antibody to reduce hepcidin levels in lung cancer may improve cancer-related anemia and anemia of inflammation in lymphoproliferative disorders." (PMID 36014824, 2022). "We tested the efficacy of anti-IL-6 antibodies in murine models of lung cancer." (PMID 35550592, 2022). "Besides growth factors, lung cancer cells produce different inflammatory modulators such as the interleukin family (IL‐6, IL‐8, IL‐17, IL‐22), tumor necrosis factor‐α (TNF‐α) and VEGF to promote their progression, invasion and angiogenesis." (PMID 35603909, 2022). "Moreover, a previous study also reported that the level of IL-1β, IL-6, and TNF-α was notably up-regulated in lung cancer with Qi-yin deficiency." (PMID 35292015, 2022). "We believe that the panel of CEA + IL-6+IL-8 could be the most effectively used in the diagnosis of lung cancer." (PMID 35928100, 2022). "We further evaluated the value of CEA, IL-1β, IL-6, and IL-8 for the auxiliary diagnosis and prognostic evaluation of lung cancer, to provide more accurate potential molecular biomarkers for the diagnosis of the patient with lung cancer." (PMID 35928100, 2022). "We identify a hitherto unknown S1P/S1PR3 axis involved in the amplification of PBMC-driven inflammation through IL-6 release in lung cancer, likely explaining the involvement of S1P in lung cancer." (PMID 36010601, 2022). "Culturing A549 or CL1-5 lung cancer cells with bone marrow mesenchymal stem cells (MSCs) can increase spheroid formation, drug resistance and overexpression of pluripotent markers by activating IL-6/JAK2/STAT3 pathway." (PMID 36591515, 2022). "This article reports a case of a lung cancer patient who developed multisystemic adverse effects after PD-1 inhibitor application: myocarditis, myositis and thrombocytopenia, and analyzes the role of Interleukin 6(IL-6)in the management of irAEs." (PMID 36119464, 2022). "Thus, we performed this work to delineate the mechanistic actions of APE1/IL‐6 signalling in Erlotinib resistance of non‐small cell lung cancer (NSCLC)." (PMID 35605028, 2022). "The study found that 8 (53%) of the 15 lung cancer cell lines expressed IL-6 mRNA and protein, suggesting that the overexpression of IL-6 may disrupt the cytokine balance and weaken the anti-tumor immunity of patients with lung cancer." (PMID 34079469, 2021). "Indeed, in lung cancer, iron-loaded TAMs enhance the generation of ROS and pro-inflammatory cytokines (TNFα and IL-6), thus inducing tumor cell death." (PMID 33540645, 2021). "In addition, AZD6244 treatment of human lung cancer cells showed a consistent upregulation of Th17-associated genes (TGF-β, IL6, IL23, IL17, IL22, IL1b, and RORγt)." (PMID 33972557, 2021). "IL6 also triggers enhanced stemness of cancer cells in solid tumors, promoting the self-renewal and preventing apoptosis of stem-like cells, especially in lung cancer, glioma, and colorectal cancer." (PMID 34638319, 2021). "Indeed, XMD 17-109 significantly reduced IL-6 secretion from the three lung cancer cell lines NCI-H226, NCI-H2122, and NCI-H1650 as well as from the two CAFs lines." (PMID 34671021, 2021). "Also, miR-218 served as a tumor suppressor in lung cancer by affecting the interleukin-6/STAT3 axis." (PMID 33896365, 2021). "However, previous studies have shown that blocked IL-6 can inhibit the progression of some lung cancers, which is obviously inconsistent with our conclusion." (PMID 34568032, 2021).
lung carcinoma (continued). "Lung cancer cell lines secrete IL-6, IL-10 and TGFβ, which are also found in pleural effusions." (PMID 33466674, 2021). "In our study, we demonstrate that IL-6 could additionally alter the antitumor immune response through modulating DCs, since IL-6 secreted from lung cancer cell lines inhibited the IL-12p70 production from LPS-stimulated moDCs." (PMID 34671021, 2021). "In our study we observed that SARS-CoV-2 infection of the lung carcinoma epithelial cell line Calu-3 triggers IL-6 expression while was unable to induce Mx1 gene expression, suggestive of a strong reduction of type I IFN production and, thus, confirming what already observed." (PMID 34473805, 2021). "Previous studies have demonstrated the IL-6 can promote lung cancer metastasis." (PMID 34589114, 2021). "NCI-H1650, another lung cancer cell line, harbors an EGFR-activating mutation and has been described as IL-6-secreting, which we could confirm in our study." (PMID 34671021, 2021). "Thus, IL-6 secretion from lung cancer cell lines is independent from the activating “driver” mutations." (PMID 34671021, 2021). "Lung cancer cell lines can secrete cytokines such as IL-6, which indicates that lung cancer may regulate the immune microenvironment by secreting cytokines." (PMID 34966411, 2021). "Regarding IL-6 our data suggest that independent of the driver mutation of the three lung cancer cell lines (NCI-H226, NCI-H2122, and NCI-H1650), treatment with XMD 8-92 significantly reduces its secretion." (PMID 34671021, 2021). "Similar results were observed in another lung carcinoma cell line H358, suggesting that PRMT5 might potentiate STAT3 activation induced by autocrine IL‐6 in lung carcinoma cells." (PMID 34026434, 2021). "The combination of CEA, IL-6, and LDH, on the other hand, may distinguish patients with stage IIIA and stage IIB lung cancer with high sensitivity and diagnostic specificity." (PMID 34439874, 2021). "Interestingly, we uncover that ERK5 plays a critical role in the regulation of IL-6 secretion from several human lung cancer cell lines." (PMID 34671021, 2021). "Prolonged sedentary behaviors are shown to increase the level of multiple inflammatory factors including tumor-necrosis factor-alpha, interleukin-6, and leptin that may contribute to the development of lung cancer." (PMID 34777480, 2021). "Additionally, in preliminary clinical trials in patients with lung cancer and cachexia, the humanized anti-IL-6 antibody tocilizumab is safe and effective against cachexia-related symptoms." (PMID 33809200, 2021). "Besides, QRHX intervention can reduce the infiltration of TAMs in tumor tissues of lung cancer mice, reduce the expression of IL-6, TNF-α, ARG-1, CD31, and VEGF, and increase the expression of inducible NO synthase (iNOS)." (PMID 33224886, 2020). "Therefore, the blockade of IL6 reprograms the TME to restrict lung cancer development and progression in experimental lung tumorigenesis models." (PMID 32219066, 2020). "TAM induces EMT through IL-6-mediated WNT pathway to promote the invasion of lung cancer cells." (PMID 33537237, 2020). "Previous studies found that IL-6 blockaded weakened lung cancer tissue construction and lung cancer stem-like cell population could be enriched through IL-6 by inhibiting cell cycle regulators." (PMID 32595734, 2020).
lung carcinoma (continued). "Nonetheless, we could show that deletion of SRC-3 expression by CRISPR-Cas9 mediated gene editing significantly decreased both, basic and TNF-α induced IL-6 mRNA expression in our A549 lung cancer cell system." (PMID 32647362, 2020). "For example, in lung cancer cells exposed to arsenic, oncogenic transformation correlates with sustained upregulation of IL6 and reduced autophagy, and IL-6-dependent transformation requires inhibition of a Beclin1-Bcl2 complex, which is dependent on STAT3 signaling." (PMID 32143356, 2020). "Indeed, several studies have confirmed that high levels of C-reactive protein, IL-6, IFN-γ, and IL-1β were positively associated with lung cancer risk." (PMID 32802852, 2020). "Given that miR-19a or miR-19b-1 mimics suppressed IL6 expression in lung cancer and NPC cells, we further investigated the possibility that ectopic miR-19a or miR-19b-1 expression could affect IL6 production by these cancer cells." (PMID 32308549, 2020). "Multivariate logistic regression analysis indicated that only OPG (P < 0.001), PTHrP (P < 0.001), tP1NP (P = 0.001), and β-CTx (P < 0.001) were independent diagnostic factors for bone metastasis in lung cancer, while CaN and IL-6 were not." (PMID 32546271, 2020). "Importantly, these investigators found that reducing the inflammatory markers, CRP and IL-6 (and likely other pro-inflammatory proteins) with canakinumab (a monoclonal antibody against IL-1β) dramatically reduced the incidence of lung cancer in these patients." (PMID 33173057, 2020). "The lung metastasis mice model was established to investigate whether knockdown of TIM‐4 could inhibit IL‐6‐enhancing metastasis of lung cancer cells in vivo." (PMID 32020709, 2020). "In this study, the serum concentrations of BME cytokines (CaN, OPG, PTHrP, and IL-6) and bone turnover markers (tP1NP and β-CTx) were analysed in 205 lung cancer patients, and these bone biochemical markers were comprehensively analysed in relation to bone metastasis in lung cancer." (PMID 32546271, 2020). "It is interesting that TIM‐4 overexpression promoted IL‐6 production in lung cancer cells." (PMID 32020709, 2020). "Tumor cells including esophageal cancer, lung cancer, colorectal cancer and melanoma were found have the function of autocrine IL-6, which can affect the growth and proliferation of tumor cells and participate in the tumor growth and metastasis by acting on the membrane receptors." (PMID 32819324, 2020). "Since NFkB signaling could regulate IL6 expression in inflammation and cancer, we further investigated IL6 expression in p65 overexpressing lung cancer cells." (PMID 32963220, 2020). "In conclusion, ERO1L might affect the secretion of CA125 through the IL6 signaling pathway and form a positive feedback loop to further promote the development of lung cancer." (PMID 33056994, 2020). "Above all, TIM‐4 could also increase IL‐6 production in lung cancer cells, which might form a positive feedback loop in IL‐6 involved lung cancers." (PMID 32020709, 2020). "Furthermore, IL-6 is known to play an essential role in lung cancer by promoting COPD-like inflammation." (PMID 33375062, 2020). "IL-6 and MCP-1 have been reported to be pathogenic markers of renal inflammation with albuminuria in patients with a variety of kidney injuries, and thus expressions of IL-6 and MCP-1 were selectively investigated in the kidneys of those lung cancer mice." (PMID 33260558, 2020). "It has been described that IL-6 and bone morphogenetic proteins (BMPs) control hepcidin secretion in different cancers such as breast and prostate cancers and IL-6 levels were increased in lung cancer patients with poor prognosis." (PMID 33255972, 2020). "Interestingly, conditioned medium from FAS knockdown cells markedly increased STAT3 phosphorylation, suggesting that increased IL6 expression by FAS knockdown is responsible for STAT3 activation in lung cancer cells." (PMID 32963220, 2020).